Y_RNA (Y RNA )
Gene: Miscellaneous RNA gene on chromosome 17 (40,391,232 to 40,391,338, reverse strand). Ensembl gene ENSG00000222881.
Homologues: Orthologues: chimpanzee Y_RNA (100% identical). Paralogues in human: RNY1 (88% identical), RNY1P11 (88% identical), Y_RNA (88% identical), RNY1P12 (87% identical), Y_RNA (87% identical), Y_RNA (86% identical), Y_RNA (85% identical), Y_RNA (84% identical), Y_RNA (83% identical), RNY1P10 (82% identical), RNY1P15 (82% identical), RNY1P8 (82% identical), and 96 more.